FAM219B (family with sequence similarity 219 member B)
Synonyms: C15orf17; FLJ00005
Tractability: PROTAC: ubiquitination databases record sites on it.
Gene: Protein-coding gene on chromosome 15 (74,899,992 to 74,907,331, reverse strand). Ensembl gene ENSG00000178761.
Subcellular location (Human Protein Atlas): Nucleoplasm; Golgi apparatus
Gene Ontology:
Molecular function: protein binding
Genetic constraint (gnomAD): Loss-of-function variants: 18 observed, 16.99 expected, observed/expected ratio (o/e) 1.06, 90% interval 0.73 to 1.57. The upper end of that interval is the gene's LOEUF score, 1.57, which puts it in group 6 of 6, group 1 being the genes least tolerant of losing a copy. Missense variants: 283 observed, 237.67 expected, observed/expected ratio (o/e) 1.19, 90% interval 1.08 to 1.31. Synonymous variants: 123 observed, 102.79 expected, observed/expected ratio (o/e) 1.2, 90% interval 1.03 to 1.39.
Homologues: Orthologues: chimpanzee FAM219B (99% identical), macaque FAM219B (97% identical), pig FAM219B (88% identical), mouse Fam219b (83% identical), rat Fam219b (83% identical), dog FAM219B (78% identical), guinea pig FAM219B (77% identical), zebrafish fam219b (43% identical), tropical clawed frog FAM219B (39% identical). Paralogues in human: FAM219A (40% identical).
Diseases named in the same sentence as FAM219B in open-access papers:
FAM219B is named in the same sentence as 4 diseases in open-access papers, as found by Europe PMC text mining. Sharing a sentence is not in itself a finding about the gene and the disease.
FAM219B shares sentences with these, for which no sentence is quoted: breast carcinoma (1 paper); Hypertension (1); Stroke (1); type 2 diabetes (1).